CDKN2B (cyclin dependent kinase inhibitor 2B)
Diseases named in the same sentence as CDKN2B in open-access papers (continued):
Sharing a sentence is not in itself a finding about the gene and the disease.
atherosclerosis (31 papers, 2009 to 2025). A disease characterized by the build-up of fatty material and calcium deposition in the arterial wall resulting in partial or complete occlusion of the arterial lumen. "From a functional perspective, CDKN2A and CDKN2B are functional candidate genes that are potentially implicated in the pathogenesis of atherosclerosis." (PMID 38149798, 2024). "And the possible association of CDKN2B methylation and atherosclerosis can be further extrapolated to patients with CAD or other cardiovascular diseases." (PMID 27905995, 2016). "And ANRIL, a lincRNA regulating CDKN2A and CDKN2B, was reported to be associated with atherosclerosis." (PMID 25628894, 2015). "Higher level of DNA methylation of cyclin dependent kinase inhibitor 2B (CDKN2B), a gene involved in the pathogenesis of both atherosclerosis and arterial calcification, was associated with increased susceptibility to calcification of the arteries in patients with IS." (PMID 31941075, 2020). "Another example is the strong association of expression levels of Cdkn2b with atherosclerosis." (PMID 26694027, 2015). "However, a recent study showed that Cdkn2b deficient mice on an ApoE deficient background develop more atherosclerosis compared to ApoE deficient mice with an intact Cdkn2b gene." (PMID 24680834, 2014). "This study argued that altered transcript levels of CDKN2B in visceral tissue may increase the risk of atherosclerosis emergence." (PMID 22216278, 2011). "Overexpression of CDKN2A and CDKN2B in murine models is associated with pancreatic islet hypoplasia and diabetes, and there is also emerging evidence that vascular cell senescence involving these pathways is involved in the pathogenesis of atherosclerosis." (PMID 20386740, 2010). "This region maps near two well-characterized tumor suppressor genes, CDKN2A and CDKN2B, encoding respectively proteins p16 INK4a and p15 INK4b, involved in the regulation of cell proliferation, cell aging and apoptosis, mechanisms that have a critical role in atherosclerosis." (PMID 20403154, 2010). "CDKN2B, a key gene in atherosclerosis, exhibits reduced calreticulin levels in Cdkn2b−/−Apoe−/− mice compared to controls, contributing to increased plaque size and necrotic core area under Western diet conditions." (PMID 39660125, 2024). "In the present study, we found diminished mRNA expression levels of CDKN2A (p16Ink4a), CDKN2A (p14Arf), CDKN2B (p15Ink4b) and CDKN2BAS genes in circulating leukocytes of T1DM patients, who also displayed increased atherosclerosis risk measured as CC-IMT." (PMID 31299986, 2019). "The MTAPand CDKN2B genes were shown to be expressed in cellsand tissues involved in the development of atherosclerosis, includingendothelial cells, macrophages, and smooth muscle cells of coronary arteries." (PMID 26483964, 2015). "Many of the genes identified are implicated in the regulation of SMC plasticity during atherosclerosis, including PDGFD, COL4A1/2, CDKN2B and CDKN2A/p19ARF." (PMID 23874238, 2013). "Expression data suggested a coordinated transcriptional regulation of ANRIL, CDKN2A and CDKN2B, and expression in tissues involved in atherosclerosis, like vascular endothelial cells, macrophages, and coronary smooth muscle cells, had been shown." (PMID 19214202, 2009). "Although the exact function is unknown, there is a remarkable relationship between the level of CDKN2B mRNA and increased atherosclerosis." (PMID 40900941, 2025). "Another study demonstrated that deletion of the targeted 9p21.3 risk locus of orthologous ANRIL interval in mice reduced the expression of CDKN2A and CDKN2B in the heart and led to excessive proliferation of vascular cells that contribute to the development of atherosclerosis." (PMID 38149798, 2024). "Markedly decreased expression of CDKN2A and CDKN2B was reported in mutant mice and doubling of the proliferative capacity of mutant aortic smooth muscle cells in culture was detected, a cellular phenotype relevant to atherosclerosis." (PMID 35653368, 2022).
atherosclerosis (continued). "CAD risk SNP rs1537373 affects CDKN2B expression in human coronary artery smooth muscle cells, aorta and the mammary artery, and CDKN2B has been shown to regulate inflammatory cytokine production and the clearance of smooth muscle cell-derived apoptotic bodies during atherosclerosis." (PMID 29868613, 2018). "Among genes regulated by 9p21 risk variants, CDKN2B appears to play a significant role in the regulation of SAT expandability, which is a strong determinant of lipotoxicity and therefore might contribute to the development of atherosclerosis." (PMID 24680834, 2014). "CAD risk alleles were all associated with reduced ANRIL expression, up to 1.9-fold, suggesting that expression of ANRIL, rather than CDKN2A or CDKN2B, might mediate atherosclerosis susceptibility." (PMID 20386740, 2010). "Further studies are necessary to investigate the pathogenesis of atherosclerosis and vascular calcification and clinical utility of genes in 9p21.3 including CDKN2A and CDKN2B." (PMID 30921371, 2019). "Recently, it has been hypothesized that the regulation of CDKN2B gene expression by lncANRIL could be involved in glucose homeostasis, while in diabetic patients, high glucose could alter ANRIL expression, favoring cell adhesion and cell proliferation, thereby leading to atherosclerosis." (PMID 29387042, 2018). "The expression of ANRIL transcripts (EU741058 and NR_003529) in atherosclerotic plaque tissue was directly correlated with severity of atherosclerosis; however, no such correlation was found in CDKN2A, CDKN2B and MTAP." (PMID 21698238, 2011).
leukemia (30 papers, 2010 to 2024). A malignant (clonal) hematologic disorder, involving hematopoietic stem cells and characterized by the presence of primitive or atypical myeloid or lymphoid cells in the bone marrow and the blood. "Another interesting study described the association between high expression of CD93 and loss of CDKN2B (p15Ink4b) expression; a cell-cycle inhibitor gene that has been shown to play a prominent role in leukemia pathogenesis and correlate with poor prognosis." (PMID 28646224, 2017). "Our results showed a significant heterogeneity among the 5 case-control studies (I2 = 56%), and revealed that hypermethylation of CDKN2B gene was associated with the increased risk of leukemia (P = 0.001, OR = 9.67, 95% CI = 2.48–37.75)." (PMID 24810788, 2014). "According to the results of our meta-analysis, the aberrant DNA methylation at CDKN2A gene and CDKN2B gene were risk factors for leukemia, especially for AML." (PMID 24810788, 2014). "It is now well established that elevated DNA methylation is an important mechanism of gene transcriptional inactivation and genes such as ESR1, IGSF4 and CDKN2B/p15 are epigenetically silenced in adult leukaemia." (PMID 24885794, 2014). "Meta-analysis of CDKN2B methylation with leukemia was carried out in 5 studies among 86 controls and 108 cases." (PMID 24810788, 2014). "DPYS, NPM2, OSCP1, PDLIM4 and TFAP2E genes were found hypermethylated, and CDKN2B (p15INK4B) homozygously deleted in the K562 leukemia cell line." (PMID 21760961, 2011). "Gene CDKN2B functionally influences tumor suppression and its methylation has been studied for its power in leukemia treatment." (PMID 20386599, 2010). "Methylation of the cytosines at the palindromic CpG sites clustered in gene promoter regions plays an important role in the epigenetic silencing of genes such as ESR1, IGSF4, and CDKN2B/p15 during the development, progression, and relapse of leukemia." (PMID 20808941, 2010). "Alternatively, expression of the convergent antisense noncoding RNA in the INK4 locus at the CDKN2B locus in leukemia cell lines resulted in repression of CDKN2B mRNA expression through increased H3K9me2 and reduced H3K4me2 histone modifications at the CDKN2B promoter." (PMID 37748649, 2023). "Single-cell multicolour FISH was used to demonstrate that the earliest detectable leukaemia subclone contained the STIL-TAL1 fusion and copy number loss of 9p21.3 (CDKN2A/CDKN2B locus), with other copy number alterations including loss of PTEN occurring as secondary subclonal events." (PMID 29556024, 2018). "A further subgroup meta-analysis by subtype of leukemia showed that CDKN2A, CDKN2B, ID4 genes were significantly hypermethylated in acute myeloid leukemia." (PMID 24810788, 2014). "We performed STAMP analysis of a human leukemia-derived cell line, M091 and evaluated STAMP results at loci that we knew to be transcriptionally silenced, (CDKN2B, p15INK4b), or robustly expressed (GAPDH)." (PMID 21267076, 2011). "Positively correlated genes such as CDKN2B and ZIC2 were reported to have anti-leukemia effects." (PMID 32209730, 2020). "Similarly, in the leukemia cell line U937, the CDKN2B-related has_piR_011186 constituted a complex with DNMT1, SUV39H1 and EZH2 proteins, upregulating the methylation level of DNA and histone H3 (including histone H3K9 and H3K27) in the CDKN2B promoter site." (PMID 35637965, 2022).
astrocytoma (25 papers, 1997 to 2025). "Presence of a CDKN2A/CDKN2B homozygous deletion is associated with particularly poor outcome of IDH-mutant astrocytoma patients, even within the group of patients with CNS WHO grade 4 tumors." (PMID 38183430, 2024). "In addition to histological Grade 4 IDH‐mutant astrocytoma, astrocytoma with IDH‐mutations of WHO Grades 2, 3 and homozygous CDKN2A and/or CDKN2B deletions are also defined as astrocytoma, IDH‐mutant, Grade 4, despite their relatively lower histopathology grades." (PMID 37667984, 2023). "Most recently, there has been considerable interest in the effect of CDKN2A and/or CDKN2B (CDKN2A/B) homozygous deletions (HD) on the prognosis of isocitrate dehydrogenase (IDH)-mutant astrocytomas." (PMID 37504251, 2023). "Genomic alterations of CDKN2A and CDKN2B in astrocytomas have been an evolving area of study for decades." (PMID 37504251, 2023). "In particular, amplification of PDGFR (platelet-derived growth factor receptor) genes, CDKN2A/CDKN2B homozygous deletion, and PI3K mutations were independently associated with worse prognosis in patients with anaplastic (WHO grade 3) astrocytomas." (PMID 35875065, 2022). "Pairwise comparison between the tumor grades indicated that the relative expression of the CDKN2A and CDKN2B transcripts was approximately 1.3-fold lower in grade IV glioblastoma compared with that in grade II astrocytoma (p<0.001)." (PMID 26317630, 2015). "Additionally, astrocytoma with IDH-mutant grade III and synonymous CDKN2B and/or CDKN2A deletions were also characterized as astrocytoma, IDH mutations, grade IV, albeit with a relatively low histopathologic grade." (PMID 38919539, 2024). "Moreover, homozygous deletion of the CDKN2A/CDKN2B tumor suppressor gene locus has been introduced as a molecular biomarker for CNS WHO grade 4 in an IDH-mutant astrocytoma." (PMID 38183430, 2024). "However, this limitation still needs to be considered when interpreting the impact of CDKN2B HD in astrocytoma patients." (PMID 37504251, 2023). "Concomitant CDKN2A and CDKN2B HDs could be detected in patients with glioblastoma multiform cancer, astrocytoma, and gliosarcoma." (PMID 33980169, 2021). "In a series of 46 glioblastomas, 16 anaplastic astrocytomas and eight astrocytomas, all tumours retaining one or both alleles of CDKN2A (48 tumours) and CDKN2B (49 tumours) were subjected to sequence analysis (entire coding region and splice acceptor and donor sites)." (PMID 9000591, 1997). "Alterations of CDK6, CDKN2A, CDKN2B, FGFR2, and MYC were more likely to be detected in WHO grade 4 astrocytoma, while variations of chromosome 19q had a higher frequency in WHO grade 2–3 astrocytoma." (PMID 38970209, 2024). "Currently, molecular markers for clinical classification, prognosis, and therapeutic response prediction of astrocytoma include MGMT promoter methylation and homozygous CDKN2A and/or CDKN2B deletions." (PMID 37667984, 2023). "Astrocytoma, IDH-mutant with homozygous deletion of CDKN2A and/or CDKN2B (CDKN2A/B-HD) carries a poor prognosis, and CDKN2A/B-HD tumors are graded as “astrocytoma, IDH-mutant, CNS grade 4,” even in the absence of histological features of necrosis or microvascular proliferation." (PMID 39636550, 2025). "An important refinement in WHO 2021 is the addition of homozygous deletion of CDKN2A and/or CDKN2B to the grading of IDH-mutant astrocytomas, related to the negative survival implications." (PMID 37316586, 2023). "These authors found that CDKN2B exhibited a uniform non-methylated pattern in all astrocytoma grades." (PMID 26317630, 2015). "Therefore, a diagnosis of astrocytoma, IDH mutant, or CNS WHO grade 4 requires either morphologic features of a glioblastoma, namely necrosis or microvascular proliferation, or homozygous deletion of CDKN2A and/or CDKN2B." (PMID 37504251, 2023).
astrocytoma (continued). "The purpose of this study was to correlate conventional MRI features with homozygous deletion of CDKN2A and/or CDKN2B, type of IDH mutation (IDH1-R132H or non-canonical) and overall survival in a cohort of histological grade 2–3 IDH-mutant and 1p/19q-non-codeleted astrocytomas." (PMID 37316586, 2023). "A recent report has found an increase of promoter hypermethylation in CALCA and CDH1 genes in high-grade astrocytomas, but they did not see any remarkable methylation frequency of other classical tumor suppressor genes, such as p14ARF, RB1, CDKN2B, or APC." (PMID 22389839, 2012).
glioblastoma (23 papers, 1997 to 2025). The most malignant astrocytic tumor (WHO grade IV). "Patients with IDH1/2-wildtype glioblastomas harboring CDKN2B, EGFR, and TERT promoter mutations who underwent GTR were associated with improved OS when compared to other EOR in the FDR-adjusted analysis." (PMID 35156038, 2022). "Bi-allelic inactivation of genes is common in cancer, including ATM in chronic lymphocytic leukemia, CDKN2A and CDKN2B in glioblastoma, and are indicative of loss of function of key tumor suppressor genes." (PMID 28234347, 2017). "Glioblastomas with retention of both alleles of CDKN2A (14 tumours) and CDKN2B (16 tumours) expressed transcripts for these genes." (PMID 9000591, 1997). "The FGFR3 glioblastoma cases exhibited the most common mutations found in IDH-wild-type glioblastoma, with CDKN2A homozygous loss in all cases, followed by PTEN mutations with LOH and CDKN2B homozygous loss, in three cases, and TERT c.124C>T promoter mutation in two cases." (PMID 33853673, 2021). "With the analysis of database Glioblastoma Multiforme (TCGA, Provisional), we found that the deletion rate of CDKN2A locus 9p21.3 was up to 57.4%, and the deletion rate of CDKN2B locus 9p21.3 was up to 56%." (PMID 32860670, 2020). "In IDHwt glioblastomas, CDKN2A, CDKN2B, and MTAP predict for poor prognosis." (PMID 36380219, 2022). "Furthermore, both cohorts exhibited significant deletion in chromosome 10, one of the major genomic features of glioblastoma, and chromosome 9, harboring CDKN2A and CDKN2B." (PMID 32794373, 2020). "In contrast, 7/13 glioblastomas with hemizygous deletions of CDKN2A and 8/11 glioblastomas with hemizygous deletions of CDKN2B showed no or weak expression." (PMID 9000591, 1997).
pancreatic cancer (21 papers, 2015 to 2025). "The cell cycle and G1-S phase transition are of a therapeutic interest in pancreatic cancer where the cycle regulator p15, encoded by CDKN2B gene is frequently deleted or mutated." (PMID 40699853, 2025). "Chromosome Conformation Capture related techniques have already been successfully applied to uncover interactions between distant regulatory elements, as occurs with CDKN2B in pancreatic cancer susceptibility or FOXL2 gene in blepharophimosis syndrome." (PMID 25701871, 2015). "ANRIL’s SNP rs1537373 may enhance pancreatic cancer susceptibility through TFs binding and Cyclin-dependent kinase inhibitor 2B (CDKN2B) expression regulation." (PMID 37888204, 2023). "The genes MACROD2 in pancreatic cancer and CDKN2B in liver cancer also show significant differential expression between samples with SVs at these loci relative to those without SVs." (PMID 36163358, 2022). "Notably, a study focusing on genetic alterations in pancreatic cancer highlighted the significance of CDKN2B deletion in tumorigenesis." (PMID 38666907, 2024). "Similarly, the inactivation of the CDKN2B gene is responsible for the progression of pancreatic cancer." (PMID 34068918, 2021). "In conclusion, we established a novel pancreatic cancer model in tree shrew and identified driver mutations indispensable for PDAC induction from acinar cells in mature adults, demonstrating the essential roles of Cdkn2b in the induction of PDAC originating from adult acinar cells." (PMID 30910991, 2019). "Our work also demonstrated that inactivation of Cdkn2b was indispensable for PDAC induction, which is similar to pancreatic cancer derived from ductal cells in mice." (PMID 30910991, 2019). "CDKN2B (encoding p15INK4b) acts as a tumor suppressor by promoting cell cycle arrest and senescence in the absence of CDKN2A, especially in pancreatic cancer." (PMID 33660437, 2021). "Contrary to prior beliefs, the study found that CDKN2B, rather than CDKN2A, plays a crucial role in inducing pancreatic cancer." (PMID 38666907, 2024). "However, looking at a single cell RNA seq data set of pancreatic cancers (GSE214295), the absence of CDKN2B expression was prominently observed in the cell population identified as ductal cells, with a more complex expression pattern of coagulation related genes." (PMID 38188342, 2023).